CRP (C-reactive protein)
Diseases named in the same sentence as CRP in open-access papers (continued):
Sharing a sentence is not in itself a finding about the gene and the disease.
infection (continued). "The mean CRP levels in patients with infection were 155.2±119.1 mg/dl." (PMID 32821576, 2020). "The inflammatory cytokines commonly used to treat infection are WBCs, CRP, PCT, and IL-6." (PMID 32864930, 2020). "The fine-tuned response of the human plasma C-reactive protein (CRP) levels to infection, inflammation or trauma makes this predominant acute phase protein (APP) one of the most studied health biomarkers, and it has been associated with predictions for cardiovascular risk and disease." (PMID 31953490, 2020). "Here we found that PD‐L1 mRNA was induced in association with higher levels of the infection marker CRP in the periphery but not with RV in the airways." (PMID 32394602, 2020). "Serum vitamin A concentrations could be affected by infection, for accurate estimation, adjusting it by CRP and/or AGP was recommended." (PMID 32731898, 2020). "Conversely, at least eight CRP peaks of magnitude equal to those linked to Crohn's attacks are not noted by the subject as either Crohn's attacks or infections." (PMID 32253915, 2020). "Further results showed that when SVCV infection was carried out in combination with the CRP-mix, the number of autophagosomes significantly increased (2.6 ± 1.1-fold) but remained similar to the number obtained when the CRP-mix treatment had been used alone (2.3 ± 0.6)." (PMID 31953490, 2020). "However, as we did with PCT, some authors reported an elevation of C-reactive protein in patients free of infection during DKA episodes." (PMID 32430795, 2020). "CRP sensitivity must be further evaluated by selecting cut-off values in various infections." (PMID 32952850, 2020). "Assays of infection markers found that C-reactive protein was increased in 23 patients (23/29; 79%), serum ferritin was increased in 16 (16/29; 55%), procalcitonin was increased in six (6/29; 21%), and the erythrocyte sedimentation rate was increased in seven (7/29; 24%)." (PMID 32582740, 2020). "Also, previously it has been suggested that SAA protein acts as a more profound marker of inflammation than the CRP and both were useful in elimination of infection by binding to the cell wall of microbes." (PMID 32470023, 2020). "However, WT CRP was found to be protective only when given to mice within 2 h of administering pneumococci in the mouse model of infection in which WT CRP is passively administered." (PMID 33552084, 2020). "C-reactive protein (CRP) is a measure of acute inflammation or infection." (PMID 32325778, 2020). "The correlations between viral loads with indexes of SARS-CoV-2 infection, including sex, age, blood routine, blood chemistry, infection-related biomarkers (CRP, PCT, and FERR), immunoglobulins, complements, B cells, NK cells, and subsets of T cells were further evaluated." (PMID 32419639, 2020). "The level of temporal detail observable by this approach provides a much more complete picture of recovery, including interruptions, than shown in previous studies using a single marker (typically CRP) to detect post-surgical infection or to assess surgical damage." (PMID 32253915, 2020). "Also, there was less exposure in the CRP group in the cumulative curve of antibiotic suspension for the first infection episode." (PMID 32487263, 2020). "Therefore, significant attention has focused on the utility of the inflammatory markers procalcitonin and C-reactive protein, both of which are widely available but have variable performance in Southeast Asia for infection prognosis." (PMID 32605575, 2020). "Also, it is unclear to what extent PCT and CRP predict the occurrence of secondary infections in these patients." (PMID 33023606, 2020). "With regard to percent changes from the resection to the reimplantation, the median percent change in the CRP was 29.99% (IQR 11.12–74.81%) for those patients who remained infection-free and 16.04% (IQR 7.02–107.32%) for those who experienced reinfection (p = 0.595)." (PMID 32887615, 2020).
infection (continued). "CRP has been established as a general biomarker of inflammation and infection in clinical practice." (PMID 32932587, 2020). "CRP level can increase in response to injury, infection, and inflammation." (PMID 33382815, 2020). "CRP is an acute phase reactant that rises 6–18 hours after infection." (PMID 32494342, 2020). "ESR and CRP are useful inflammatory markers for diagnosing and monitoring infections." (PMID 32616029, 2020). "In addition, the relationship between CWA and existing biological markers in infections (CRP and procalcitonin) was explored." (PMID 32843693, 2020). "Furthermore, the risk of infection was assessed using objective indicators like IL-6, PCT, ESR, and CRP which eliminated observer bias." (PMID 32846864, 2020). "The ITT analysis revealed that the median duration of antibiotic therapy in the index episode of infection was similar in both groups, with first and third quartiles showing higher values in the control group: 7 (5–8.8) days in the CRP group versus 7 (7–11.3) days in the control group (p = 0.011)." (PMID 32487263, 2020). "The usual lab markers for the detection of an infection, such as leukocyte count or C-reactive protein (CRP), may initially also be normal or only minimally altered." (PMID 32373430, 2020). "Furthermore, as there is an evident relationship between CRP and the leukocyte count, we argue that infections should be accounted for in ALL MT predictive modelling." (PMID 31792398, 2019). "Additionally, the serological tests (ESR, CRP and IL-6) showed poor sensitivity and specificity in predicting persisting infection before second-stage prostheses implantation." (PMID 31159792, 2019). "In this study, we also aimed to evaluate whether serum PCT or CRP levels could differentiate infection etiologies in febrile patients with hematologic disorders." (PMID 31821331, 2019). "Another challenge seems to be the differentiation of inflammation and infection using CRP." (PMID 31022834, 2019). "We hypothesised that since serum AGP and CRP are biomarkers of inflammation, their concentrations during pregnancy may reflect clinical or subclinical infection that may contribute to FGR and small infant size." (PMID 31469064, 2019). "Maternal infection was associated with a 7% lower CRP level (95% CI, − 17,5%) among offspring compared with offspring born to women without an infection and similarly an 8% lower level of IL-6 (95% CI -15,1%), and a 9% lower level of IL-10 (95% CI, − 23,20%)." (PMID 30923624, 2019). "The preoperative work-up (CBC, ESR, CRP), performed to exclude infection, was normal." (PMID 30931898, 2019). "Other infection parameters, namely CRP and neutrophil levels were similar in both groups." (PMID 31993410, 2019). "We investigated whether early infection and an enhanced inflammatory response had carryover effects in terms of chronic inflammation by assessing CRP in plasma when mice were 469 and 795 days old." (PMID 30697342, 2019). "Last not least, we have to address the fact that we cannot provide data on additional inflammation markers such as procalcitonin or interleukin-6 as a study limitation since procalcitonin has a higher diagnostic accuracy than CRP and interleukin-6 increases in early infection stages inducing CRP." (PMID 30970668, 2019). "Additionally, CRP plays critical roles in the host response to infection and inflammation, such as the complement pathway, recruitment of leukocytes, facilitation of apoptosis and phagocytosis, and production of nitric oxide and cytokines." (PMID 31821367, 2019). "In addition, we carried out additional analyses using CRP levels >1 mg/L to define ‘elevated CRP’, and >10 mg/L to define ‘very high CRP’ indicative of current infection." (PMID 31258105, 2019). "In CS1, CS2, and A2, the CRP levels were elevated due to the ongoing infection." (PMID 30704507, 2019).
infection (continued). "Although numerous serological markers for PJI have been evaluated in the past, including interleukin 6 (IL-6), erythrocyte sedimentation rate (ESR) and C-reactive protein (CRP) have been generally used as a screening test for infection because of their simplicity and cost-effectiveness." (PMID 31358018, 2019). "In another study, it was reported that both PCT and CRP could be used in making the diagnosis of infection, but that PCT was superior for determining the prognosis." (PMID 31691767, 2019). "Third, several patients experienced signs of infection and a rise of CRP during the study period." (PMID 30823916, 2019). "Another systematic review of clinical trials of host biomarker testing for the identification of serious infections in children concluded that CRP tests could be diagnostically useful, but more evidence was needed on specific thresholds." (PMID 30554748, 2019). "Therefore, CRP has been extensively used in clinical diagnoses, including for acute infectious diseases, postoperative infection monitoring, and antibiotic efficacy observation." (PMID 31101112, 2019). "Thus, PTX3 has a different kinetics of production and different patterns of recognized ligands from CRP, a much more widely used biomarker of inflammation and infection." (PMID 31057548, 2019). "CRP was also used to diagnose infection in previous studies." (PMID 30800678, 2019). "One such study of over 1300 microbiologically confirmed infections in patients across southeast Asia found a sensitivity of 86% and a specificity of 67% for CRP at a threshold of 20 mg/L, with an area under the curve of the receiver operating characteristic of 0·83 (95% CI 0·81–0·86)." (PMID 30554748, 2019). "FCN1 may also interact with C-reactive protein (CRP) via a conformational change induced by mild acidosis at the local site of infection, and with pentraxin 3 (PTX3) in a Ca2+-dependent manner." (PMID 31694344, 2019). "Raised CRP levels are associated with recent infection with or without clinical evidence of disease." (PMID 31501455, 2019). "A high CRP level is a general indication of an infection in the body." (PMID 30886857, 2019). "After excluding patients with suspected infection, the prevalence of elevated CRP is one in two." (PMID 31258105, 2019). "Serum procalcitonin (PCT) and C-reactive protein (CRP) are biomarkers of infection." (PMID 31821331, 2019). "The following information was collected from each patient: sex, age, past medical history, site of infection, etiology, admission or outpatient care, level of C-reactive protein (mg/dL), fascial spaces involved, treatment method, and duration of hospitalization." (PMID 31815113, 2019). "CRP is a common clinically used infection diagnosis biomarker that is rapid and inexpensive and may be a good partner to refine the diagnosis of infection." (PMID 30976022, 2019). "PCT combined with CRP was used for the diagnosis of infection, LDH combined with CRP was used for the diagnosis of tumour progression in non-infected children, and the combination of three indices were used for the diagnosis of infection combined with tumour progression." (PMID 30976022, 2019). "There was a significant positive association between P-selectin and infection intensity (r = 0.172; p = 0.002) while resistin and CRP did not have a significant association with infection intensity." (PMID 31856765, 2019). "This reduces the potential for selection bias, where tests might perform better for certain disease outcomes due to GPs pre-selecting those at higher risk to have a specific test, for example, preferentially using CRP when an infection is suspected." (PMID 31208975, 2019). "The binding of calcium to CRP may also serve to protect CRP from proteolytic degradation and denaturation in circulation during the acute phase of infection." (PMID 31151201, 2019).
infection (continued). "Age, BMI and a self-reported current infection were associated with the CRP concentrations, while none of the independent variables was associated with SP-D." (PMID 30678045, 2019). "We also carried out a number of sensitivity analyses; for example, meta-analyses using >1 and >3 mg/L thresholds for CRP were repeated using only studies that excluded patients with suspected infection (defined as CRP >10 mg/L); and after excluding poor quality studies." (PMID 31258105, 2019). "Therefore, PCT and CRP can serve as infective indicators for diagnosis of paediatric tumour with infection." (PMID 30976022, 2019). "However, CRP levels have also been reported to be elevated in both infection and AE-IP, but are much higher in infection than in AE-IP." (PMID 31307466, 2019). "CRP is an important inflammatory marker whose levels rise in response to infection or trauma." (PMID 31312573, 2019). "Expression of tonguefish CRP is upregulated by pathogen infection." (PMID 31114584, 2019). "Even though the liver synthesizes CRP in response to certain factors released by macrophages and adipocytes, owing to its comparatively short half-life of 18 hours, CRP level in blood can be monitored frequently and utilized as a marker for resolution/worsening of infection as well as inflammation." (PMID 31065202, 2019). "The acute-phase response is a clinical indication of an inflammatory event such as infection, trauma, or neoplasia and is characterized by the production and secretion of acute-phase proteins, including C-reactive protein and acute-phase serum amyloids by the liver." (PMID 31183403, 2019). "During infection by pathogens, the CRP level increases within 6–8 h and peaks after 36–50 h." (PMID 31671729, 2019). "CRP serves as an early marker of inflammation in an acute-phase of infection process." (PMID 31683812, 2019). "All serologic tests showed poor prognostic value in predicting persisting infection, with the AUC of 61.6% (95% CI, 42.2 to 80.2%) for CRP, 57.8% (95% CI, 37.2 to 78.8%) for ESR, 60.3% (95% CI, 43.5 to 73.3%) for IL-6, and 62.1% (42.4 to 81.0%) for the combination of the three tests." (PMID 31159792, 2019). "Mice transgenic for human CRP are also protected against infection with S. pneumoniae." (PMID 30863393, 2019). "CRP is in clinical practice often used as an infection or inflammation screening test." (PMID 32082531, 2019). "In addition, CRP and ferritin show similar behavior in response to infection—rapid increase with onset of inflammation—however, ferritin remains elevated longer than CRP." (PMID 31500264, 2019). "In diagnosis of infections, CRP marginally outperforms both ESR and PV." (PMID 31208975, 2019). "Recently, there is growing evidence that CRP plays an important role in inflammatory processes and host responses to infection including the complement pathway, apoptosis, phagocytosis, nitric oxide release, and the production of cytokines, particularly IL-6 and TNF-α." (PMID 31333451, 2019). "Although studies have shown that CRP levels increase during infections and inflammatory diseases, the precise role of CRP isoforms in their development and progression remains largely unknown." (PMID 29706967, 2018). "This is an important observation, since the use of CRP as a tool to diagnose bacterial infections may be grossly misleading late in the course of an infection." (PMID 29473432, 2018). "Finally, we repeated the analyses testing between infection burden and IL-6/CRP after re-categorising the infection burden variable into quartiles." (PMID 29198208, 2018). "As a result, CRP is used as a biomarker for inflammation and infection." (PMID 29892284, 2018). "However, serum CRP data suggest that dialysis centers should closely monitor signs of infection on HHD, including tenderness and localized redness at the buttonhole site." (PMID 30314451, 2018).
infection (continued). "CRP is reflective of systemic changes in infection, and its level is the measurement of acute phase reactants, which can be specifically utilized to improve the specificity of the combined algorithm, given that its reasonably high sensitivity and acceptable specificity for detecting infection." (PMID 30470789, 2018). "Intervention: Half of the children with non-severe acute infections (random allocation of practices to perform POC CRP or not) and all children at risk for serious infection were tested with POC CRP." (PMID 30354904, 2018). "Our main aims were to describe serial serum suPAR concentrations in patients with severe AKI, to investigate a potential association between suPAR and C-reactive protein (CRP), and to compare suPAR and CRP as diagnostic markers of infection in patients with AKI." (PMID 30071826, 2018). "CRP can assess the extent of infection and monitor antibiotic treatment." (PMID 29968788, 2018). "Thus, biomarkers of inflammation or infection, such as procalcitonin (PCT) and C-reactive protein (CRP), have been proposed as a guide in the diagnostic process." (PMID 30285748, 2018). "Although this study suggested that PCT and CRP could be the markers to diagnosepulmonary infection, there are some potential biases and limitations in our study.First, the increase of antibiotic therapy may reduce the levels of PCT and affectthe results." (PMID 29846409, 2018). "When considering that CRP usually starts to increase after 24 h of infection start, measuring WBC and IG percentage may help to identify children with SBI at a very early stage helping clinical decision makers to start treatment accordingly." (PMID 30344287, 2018). "Recently, the CRP/albumin ratio, a combination of markers for systemic inflammation and nutritional status, has been extensively studied as an independent prognostic marker in patients with infection, malignancy, and other diseases." (PMID 30297655, 2018). "Still, CRP concentrations also increase when there is an infection at other areas in the body." (PMID 30423942, 2018). "The ESR/CRP ratio may be useful to differentiate between infection and flare in SLE patients, where a ratio above 15 was significantly correlated with disease activity and a ratio below two was associated with infection." (PMID 29581911, 2018). "CRP was associated with infection in Kruskal-Wallis test, but not with survival in a Cox Regression model." (PMID 30018308, 2018). "Current evidence suggests that IG percentage may perform better in the early diagnosis of severe infection than for instance CRP or WBC." (PMID 30344287, 2018). "If both ESR and CRP are abnormal, it is highly indicative of infection." (PMID 30291260, 2018). "If the elevated CRP level is caused by factors other than infection, arthroplasty does not need to be delayed simply because of the elevated preoperative CRP level." (PMID 29854731, 2018). "Moreover, C-reactive protein (CRP) using 12.15 mg/L cut-off value proved to be more accurate than procalcitonin in identifying patients with infection." (PMID 29623264, 2018). "The overall pattern of association between infection burden and IL-6/CRP was similar between groups with and without atopic disorders." (PMID 29198208, 2018). "In the follow-up period, an NLR equal or greater than 3.54 may be a better test than CRP (5 mg/dL and above) for recognizing an infection and need for hospitalization." (PMID 30234089, 2018). "We suggest that both PCTand CRP levels may be helpful in diagnosing infections and distinguishing betweendifferent pathogens." (PMID 29846409, 2018). "To see whether the distribution was influenced by any current infection, we investigated the effect of excluding individuals with an elevated CRP level." (PMID 30002404, 2018).